FAP (fibroblast activation protein alpha)
Diseases named in the same sentence as FAP in open-access papers (continued):
Sharing a sentence is not in itself a finding about the gene and the disease.
tumor (continued). "These are reported to overexpress FAP and are responsible for supporting tumor progression, modulating the immune response within the TME, and inducing radioresistance." (PMID 38102692, 2023). "FAP constitutes an important target for tumor treatment; however, the current studies on FAP are mainly related to structural characteristics, enzymatic properties, and biological functions, and aptamers of FAP have not been investigated." (PMID 36838669, 2023). "The relationship between FAP expression and clinical prognosis, DNA methylation, and tumor-infiltrating immune cells in pan-cancer was assessed using R Studio (version 4.2.1)." (PMID 37490719, 2023). "FAP-expressing cells in the tumor microenvironment have been specifically and directly removed using infrared photoimmunotherapy (NIR-PIT), a new and novel method to remove CAFs." (PMID 37784082, 2023). "A recent study further consistently showed that tumor-promoting FAP-positive CAFs and tumor-restraining α-SMA–positive CAFs regulate signaling pathways differently." (PMID 37099374, 2023). "Injection with rAd‐FAP/hlivin α‐transduced DCs promotes immune‐enhanced tumor microenvironment by decreasing CAFs and suppresses tumor growth in LLC mouse models." (PMID 37773704, 2023). "Once the FAP+ tumor is visualized, the development and use of an anti-FAP drug would lead to the attack of the fibrous “niche” that the tumor exploits to protect itself." (PMID 37892020, 2023). "FAP OE NK92 cells showed significantly increased invasion into tumor spheroids and significantly increased cleaved caspase-3 expression." (PMID 38196606, 2023). "First, FAP-2286 peptide was employed as the tumor-targeting ligand, whose high binding affinity and retention are advantageous for prolonged intraoperative fluorescence guidance." (PMID 38026901, 2023). "FAP is expressed in both the primary CRC tumor and the first metastasis but it is significantly reduced in the metastatic site." (PMID 37892020, 2023). "For example, in a murine model of MSS CRC, FAP-expressing fibroblasts discouraged anti-tumor responses to anti-PD1 treatment by instilling an immunosuppressive environment through recruitment of MDSCS." (PMID 37849752, 2023). "Further modifications will be explored to improve the binding affinity, pharmacokinetics, and tumor uptake to generate promising PSMA/FAP bispecific radioligands for imaging and radioligand therapy of mCRPC." (PMID 36770755, 2023). "The results of our study unequivocally demonstrate that the dynamic detection of serum FAP serves as a straightforward approach to ascertain treatment response and evaluate tumor status." (PMID 37864148, 2023). "Most importantly, the levels of serum FAP exhibited a decline in response to therapy, while conversely, they demonstrated an increase in the presence of tumor progression." (PMID 37864148, 2023). "The results showed that tumor-to-background ratios of FAP-specific PET were almost similar to 18F-FDG-PET." (PMID 39355049, 2023). "[18F]3 showed selective accumulation in the cellular study and PET imaging study with FAP-positive cell lines and tumor models, and the blocking studies confirmed specific binding to FAP." (PMID 37057133, 2023). "There is ample evidence that FAP contributes to TME immunosuppression, thereby causing rapid tumor growth and treatment resistance." (PMID 37509656, 2023). "In the current study, we successfully screened a tumor-specific antigen Nb (FAP Nb) with good specificity and affinity for the first time." (PMID 38031188, 2023). "For example, FAP+ fibroblasts, proliferative fibroblasts, and pericytes are significantly enriched in tumor tissues, while NT5E+ fibroblasts, FGFR2+ fibroblasts, ICAM1- terminal fibroblasts, and MFAP5+ myofibroblasts are enriched in adjacent normal tissues." (PMID 38187388, 2023). "Locally targeting T cells to FAP+ stromal cells led to high infiltration of T cells to the tumor sites in mouse melanoma and human lung and breast cancer models." (PMID 38022679, 2023).
tumor (continued). "A significant decrease of CAR copies in tumor tissue was found 7 days compared with 14 days after T cell infusion in the FAP-mBBZ CAR-T treated group." (PMID 37046312, 2023). "Based on our findings, it is also possible to state that the use of FAP in tumor diagnostics is able to provide better estimates when employed to evaluate the not-metastasizing primary tumor." (PMID 37892020, 2023). "Future studies are needed to further categorize FAP expression in tumor immune cell populations, potentially using multicolor immunofluorescent staining." (PMID 38196606, 2023). "A phase I open-label dose-escalation trial was carried out to evaluate the safety, pharmacokinetics, and tumor uptake of Sibrotuzumab, a humanized version of the murine anti-FAP mAb F19." (PMID 37316886, 2023). "IHC analysis of advanced NSCLC tumor tissues showed that FAP was mainly expressed in the cytoplasm of CAFs in the tumor stroma, which was consistent with previous studies." (PMID 35951090, 2023). "To characterize the expression of FAP in cancers, we first analyzed the expression of FAP in tumor tissues and normal tissues from the TCGA database." (PMID 35951090, 2023). "FAP expressing cancer-associated fibroblasts (CAF) are the predominant component in the stroma of CRC and have been recognized as co-responsible for tumor growth and metastasis." (PMID 37614665, 2023). "In terms of DDS, carriers with surface modification of FAP derived from tumour cells turned out to induce strong CTL responses against FAP+CAFs and modified TME." (PMID 37403792, 2023). "Radionuclide-labelled FAPI can be used for detecting FAP and CAFs, which are abundant in the tumour stroma of > 90% epithelial carcinomas." (PMID 36495325, 2023). "Due to the similar functional homology and the 89% shared sequence identity between murine and human-FAP, studies have shown that murine-FAP also promotes tumor growth in cell derived xenografts." (PMID 37284857, 2023). "A prospective exploratory imaging clinical trial with 68Ga-FAPi-46 PET demonstrated that tracer uptake and biodistribution across multiple cancers strongly correlated with FAP expression of surgically excised tumor and metastasis tissues." (PMID 37046676, 2023). "FAP-targeted CAR-T cells inhibited tumor growth for a short time in both PDAC models, even though the second infusion was administrated." (PMID 37046312, 2023). "Tumor-promoting immunosuppressive activity of FAP+ fibroblasts is connected with the inhibition of TNFα signaling." (PMID 36793444, 2023). "This suggests that FAP+ fibroblasts mediate phosphorylation of Rb, which in its unphosphorylated form arrests cells in the G1 phase, thus supporting tumor cell proliferation." (PMID 38313431, 2023). "In subsequent work, for the purposes of constructing engineered T cells with dual-targeting of CAF and tumor cells, the FAP aptamer can be modified to CAR-T cells or co-modified with another aptamer onto T cells." (PMID 36838669, 2023). "The combination of fluorouracil and FAP-targeted NIR-PIT resulted in a 70.9% tumor reduction compared to only 13.3% by fluorouracil alone." (PMID 37686288, 2023). "Eighty-five percent (85%) of human (33/39), 76% of canine (40/53), and 92% of feline (22/24) STSs showed FAP positivity in over 10% of the tumor cells." (PMID 37727209, 2023). "Here, the specific deletion of FAP-positive fibroblasts led to tumor inhibition in subcutaneously mice models of lymphoma, mesothelioma, and breast, colon, and lung adenocarcinoma." (PMID 37686288, 2023). "CAR T-cell therapy, with their higher sensitivity for low antigen expression and self-amplification properties, can thus be a promising alternative strategy for targeting FAP+ tumor stromal cells." (PMID 37251405, 2023). "Further in vitro studies are needed for the characterization and measurement of FAP expression of mesenchymal tumor cells." (PMID 37727209, 2023).
tumor (continued). "Previous reports have demonstrated that in many tumor types CAFs with high FAP expression are enriched in the TME." (PMID 37086273, 2023). "In parallel, we utilized multiplex-immunofluorescence (IF) to map the intra-tumoral localization of CAR T cells (GFP+ cells) in vivo and to determine their spatial relationships with their respective FAP+ stromal cell and EpCAM+ tumor cell targets." (PMID 37607999, 2023). "Radiotracers based on FAP-2286 have been evaluated at preclinical and clinical levels demonstrating selectivity towards FAP, high tumor uptake, high tumor retention, potential anti-tumor activity, and acceptable toxicity." (PMID 37370912, 2023). "Using Cox's univariate proportional hazards analysis, FAP high mRNA levels in residual cancer stroma after preoperative CRT showed a positive correlation with the incidence of tumor recurrence." (PMID 37316886, 2023). "Our findings reveal that both knockout and inhibition of FAP restrict NK cell tumor infiltration, and attenuate NK cell-mediated tumor cell lysis, underscoring the critical role of FAP-mediated migratory mechanisms in the anti-cancer activity of NK cells." (PMID 38196606, 2023). "In order to explore the correlation between serum FAP expression and tumor characteristics, we conducted an analysis of serum FAP levels and their association with imaging observations." (PMID 37864148, 2023). "Then, GEPIA2 was employed to combine all tumor expression data of TCGA and obtained the top 100 genes that significantly correlated with FAP expression." (PMID 37166418, 2023). "It will be of interest to compare [68Ga]Ga-FAPI-04 with [68Ga]Ga-AV02070 or [68Ga]Ga-AV02053 in the clinic to investigate if pyridine-based FAP-targeted tracers can still lead to better tumor-to-background contrast, and hence, a better detection sensitivity." (PMID 36986548, 2023). "The quantitative real-time PCR was performed to assess the expression of fibrosis-related genes (including E-cadherin, α-SMA, FAP, and Cav-1) in the fibroblasts of the tumor microenvironment." (PMID 38045487, 2023). "Tumor masses on day 13 pi with 177Lu-FAP-2287 plus anti-PD-1 treatment were smaller at 424 mg than vehicle controls which were 1433 mg." (PMID 37086273, 2023). "In this context of mobilization, diffusion, and dynamism, it would be counterproductive for the tumor itself to continue to express high levels of FAP." (PMID 37892020, 2023). "Tumor bearing mice were treated with vehicle, 177Lu-FAP-2287 (60 MBq), anti-PD-1 (10 mg/kg) and the combination (n = 12 per group)." (PMID 37086273, 2023). "These chelator-conjugated small molecule FAPI agents exhibit theragnostic potential with the combined benefit of imaging and radiotherapy delivery to FAP-expressing tumor stromal cells." (PMID 37126137, 2023). "Although the probe did not serve its primary purpose of atherosclerosis imaging, the authors presented its relevance as a radiotracer for imaging FAP-positive tumor tissues." (PMID 37375746, 2023). "We observed that MFAP5 + and FAP + fibroblasts had the highest number of communications with other stromal and immune cells in the tumor, indicating their active biological properties." (PMID 37344903, 2023). "In conclusion, our study offers new insights into the oncogenic and immunological role of FAP from a pan-cancer perspective, providing new clues for developing novel targeted anti-tumor strategies." (PMID 37166418, 2023). "FAP-targeting CAR-T cells have shown promising anti-tumour responses, enhancing the activity of CD8+ T cells, which deplete tumour stroma and reduce vascular density, both of which promote tumour progression and metastasis." (PMID 39935547, 2023). "The therapeutic activity of IL2-7NP2-TNFmut was compared with IL2-F8-TNFmut in immunocompromised tumor-bearing mice, in which FAP was expressed on tumor cells whereas EDA was present in the tumor stroma." (PMID 37092450, 2023).
tumor (continued). "The phenotype of T cells in tumor tissue was tested via flow cytometry to evaluate the potential effect of FAP-mBBZ CAR-T cells on the infiltration of T cells." (PMID 37046312, 2023). "Considerable uptake in organs presenting FAP expression and tumor lesions was observed, which makes the images easy to interpret." (PMID 37284857, 2023). "Accordingly, IHC analysis indicated that the expression of FAP—a marker of CAFs—overlapped with tumor areas displaying increased platinum uptake." (PMID 36765091, 2023). "Immunization with rAd‐FAP/hlivin α‐transduced DCs enhanced the cytotoxic effect of splenic lymphocytes on LLC tumor‐derived CAFs." (PMID 37773704, 2023). "Compared with the control group, xenograft tumor volumes and weights were significantly lower in the si-FAP group after 35 days." (PMID 37752545, 2023). "The majority of tumor samples had positive FAP staining of stromal cells (77.7%) and tumor cells (50.7%)." (PMID 37333052, 2023). "Meanwhile, increased expression of miR-630, miR-200c, and miR-155-5p resulted in the upregulation of FAP levels in some tumor diseases." (PMID 37006278, 2023). "The FAP-positive tumor area was larger in STS compared to healthy and peritumoral tissue samples (p < 0.0001)." (PMID 37727209, 2023). "FD2 was created by incorporating a 4-(p-iodophenyl) butyric acid moiety into FAP-2286, with the objective of extending in vivo circulation and enhancing tumor uptake." (PMID 38706713, 2023). "The expression of POSTN (R=0.521) and FAP (R=0.606) was correlated with that of CD163 (p<0.001), which is a characteristic gene of tumour-associated macrophages (TAMs)." (PMID 37199594, 2023). "A substantial correlation was observed between the level of serum autoantibody relative FAP and tumor volume among the subjects." (PMID 37864148, 2023). "A vaccine against the tumour antigens survivin and FAP decreased the proportion of immunosuppressive cells and increased lymphocyte infiltration in a pancreatic cancer murine model." (PMID 37240052, 2023). "FAP is only highly expressed in pathological tissues, including RA-lesioned synovial tissues and various tumor stromal tissues." (PMID 37006278, 2023). "This discrepancy can be attributed to various factors, such as the interplay between FAP-expressing CAFs and tumor cells, the immunosuppressive effects of FAP, and the overall composition and dynamics of the TME." (PMID 37490719, 2023). "FAP-positive CAF subpopulations accumulate in cancers with poor prognosis and are linked to tumor progression and immunosuppression." (PMID 36864362, 2023). "Under tumor microenvironment, FAP-MB-5, whose fluorescence and photoactivity were initially quenched, was activated by recognition towards FAPα with enzymatic reaction, followed by 1,6-elimination to release photosensitizer MB and GSH consumption agent AQM." (PMID 35664057, 2022). "Injection of chimeric antigen receptor (CAR) T-cells constructed with anti-FAP mAb effectively depleted FAPhi stromal cells and inhibited tumor growth." (PMID 35222418, 2022). "The findings of the analyses indicate high radiotracer stability in human serum (>95% at 24 h), specific recognition for FAP, high tumor uptake (7.05 ± 1.13% ID/g at 30 min) and fast kidney elimination." (PMID 35011496, 2022). "Biodistribution images after therapy revealed not only significant tumor uptake of 177Lu-FAP-2286 but also long retention of the radiopharmaceutical in all patients." (PMID 34168013, 2022). "Thus, FAP+CAFs may be functionally associated with the metastatic potential of tumor cells." (PMID 36401232, 2022). "Several strategies have been explored in cancer immunotherapy by targeting FAP in tumor models, which can be applied in treating RA." (PMID 35252279, 2022). "The relatively specific expression of FAP in the tumor microenvironment has made it possible to develop FAP inhibitors (FAPIs)." (PMID 35202189, 2022).
tumor (continued). "We observed a greater extent of FAP-uptake in primary tumor sites with higher tumor-to-background ratios and in some cases detected additional (contralateral) lymph nodes as well as further suspicious distant lesions." (PMID 35771317, 2022). "Growing evidence has also suggested that FAP+CAFs can promote the immunosuppressive tumor microenvironment." (PMID 35222418, 2022). "To validate our findings in other tumor types, we assessed FAP mRNA expression across 947 human cancer cell lines from the Cancer Cell Line Encyclopedia (CCLE)." (PMID 35052475, 2022). "High FAP expression in tumor cells was more frequently found in patients with vascular invasion (p = 0.013) and positive PD‐L1 expression (p < 0.001)." (PMID 35818720, 2022). "A significant difference in the tumor area infiltrated by CD8+ T cells between FAP-IL2v-treated and vehicle-treated groups was detected only at 5 days after baseline imaging (P = 0.038)." (PMID 35874707, 2022). "Based on successful targeting of FAP in preclinical tumor models, 68Ga-OncoFAP was applied in clinical imaging in a total of 12 patients with various cancers based on clinical indications." (PMID 34957527, 2022). "This analysis predicted that tumor-specific FAP+ fibroblasts likely originated from FGFR2+ fibroblasts or ICAM1+ telocytes." (PMID 35365629, 2022). "Studies using mouse models have shown that FAP-CAR T cells can exhaust FAP-expressing stromal cells and inhibit tumor growth by producing immunostimulatory cytokines, promoting tumor cytolysis, and enhancing the anti-tumor response of endogenous CD8+ T cells." (PMID 36263225, 2022). "An interesting target is the marker FAPα, which has been identified as a promoter of tumor growth, as its genetic deletion resulted in delayed tumor development and attenuation of metastasis." (PMID 35712663, 2022). "The findings also correlated with circulating tumor markers and with 68Ga-FAP-2286 PET/CT findings (performed on 10 patients)." (PMID 34168013, 2022). "Taken together, our results show that FAPα induces CXCL5 secretion in HSCs to promote tumor cell EMT and MDSC recruitment through activation of CXCR2, thus facilitating vessel co-option." (PMID 35951441, 2022). "We found that elevated levels of YAP1 and FAPα in stromal fibroblasts were significantly correlated with NPC tumor fibrosis and poorer metastasis-free survival." (PMID 35986369, 2022). "For example, FAP has been used as a molecular marker in the identification of subpopulations of circulating tumor cell." (PMID 36263225, 2022). "We then investigated the impact of soluble factors released from tumor cells on FAP expression by primary fibroblasts isolated from murine skin tissue." (PMID 36230765, 2022). "In multivariate analyses, high FAP expression in tumor cells was an independent predictive factor of both overall survival (OS; HR = 2.57, 95% CI: 1.49–4.42, p < 0.001) and recurrence‐free survival (RFS; HR = 2.13, 95% CI: 1.38–3.29, p < 0.001)." (PMID 35818720, 2022). "Theranostic targeting of FAP in the tumor stroma provides a new therapeutic idea for the treatment of patients with systemic metastases including multiple bone metastases and metastases in other tissues and organs." (PMID 34870727, 2022). "FAP expression was an excellent predictor of CMS4 in a composite dataset of 3232 primary tumours, with an area under the receiver-operating characteristic curve (AUROC) of 0.91 (95% confidence interval [CI] = 0.89–0.92)." (PMID 35296803, 2022). "The results show an abundance of ECM proteins, such as collagens, and remodeling enzymes (BGN, FAP) in tumor tissue, compared to the normal tissue." (PMID 35328635, 2022). "During circulation, EB-FAPI-02 will bind to albumin in a dynamic way, and will be released from albumin when in proximity with FAP in the tumor stroma." (PMID 34987657, 2022). "As FAPI binds to FAP in the tumor microenvironment, it can provide insight in the biological characteristics of tumors." (PMID 36428657, 2022).